CFHR3 (complement factor H related 3)
Description:
Might be involved in complement regulation.
Synonyms: FHR-3; CFHL3; FHR3; HLF4; DOWN16
Tractability: Antibody: UniProt places it where antibodies can reach, with medium confidence; UniProt predicts a signal peptide or a membrane-spanning region; its Gene Ontology location is reachable by antibodies, with medium confidence.
Gene: Protein-coding gene on chromosome 1 (196,774,742 to 196,797,364, forward strand). Ensembl gene ENSG00000116785.
Subcellular location: Secreted
Subcellular location (Human Protein Atlas): Vesicles; Predicted to be secreted
Pathways (Reactome):
Immune System: Regulation of Complement cascade
Gene Ontology:
Molecular function: protein binding; complement component C3b binding
Biological process: complement activation
Cellular component: blood microparticle; extracellular exosome; extracellular region
Genetic constraint (gnomAD): Loss-of-function variants: 20 observed, 22.31 expected, observed/expected ratio (o/e) 0.9, 90% interval 0.63 to 1.3. The upper end of that interval is the gene's LOEUF score, 1.3, which puts it in group 5 of 6, group 1 being the genes least tolerant of losing a copy. Missense variants: 234 observed, 305.94 expected, observed/expected ratio (o/e) 0.76, 90% interval 0.69 to 0.85. Synonymous variants: 85 observed, 101.58 expected, observed/expected ratio (o/e) 0.84, 90% interval 0.7 to 1.
Homologues: Paralogues in human: CFHR4 (72% identical), CFH (67% identical), CFHR5 (41% identical), CFHR2 (39% identical), CFHR1 (36% identical), F13B (31% identical), PAPPA (22% identical), PAPPA2 (20% identical), CSMD3 (20% identical), CSMD1 (19% identical), SVEP1 (19% identical), SRPX (18% identical), and 27 more.
Diseases named in the same sentence as CFHR3 in open-access papers:
CFHR3 is named in the same sentence as 61 diseases in open-access papers, as found by Europe PMC text mining. Sharing a sentence is not in itself a finding about the gene and the disease. The quoted sentences say what the papers report.
age-related macular degeneration (11 papers, 2013 to 2023). Age-related loss of vision in the central portion of the retina (macula), secondary to retinal degeneration. "Dysregulation of CFHR3 has been associated with a series of diseases, including age-related macular degeneration, atypical hemolytic uremic syndrome and cancers." (PMID 35549979, 2022). "This 71-kb deletion spans the entire CFHR1 and CFHR3 locus that is associated with an increased risk of the hemolytic uremic syndrome and a decreased risk of age-related macular degeneration." (PMID 33420067, 2021). "For example, a common CFH haplotype with deletion of CFHR1 and CFHR3 genes associated with lower risk of age-related macular degeneration was identified using the GStream CNV calls." (PMID 23844243, 2013). "For example, CFHR3 and CFHR1 are associated with age-related macular degeneration and systemic lupus erythematous." (PMID 23594316, 2013). "Complement Factor H-Related 3 (FHR-3) is a major regulator of the complement system, which is associated with different diseases, such as age-related macular degeneration (AMD)." (PMID 34819935, 2021). "The absence of both copies of CFHR3 and CFHR1 is also associated with a lower risk of age-related macular degeneration (AMD) and IgA nephropathy, and a higher risk of atypical haemolytic uremic syndrome (aHUS) and systemic lupus erythematosus (SLE)." (PMID 34211499, 2021).
atypical hemolytic-uremic syndrome (9 papers, 2011 to 2025). A rare, genetic thrombotic microangiopathy due to dysregulation of the alternative complement pathway and characterized by the triad of hemolytic anemia, thrombocytopenia, and acute renal dysfunction. "Dysregulation of CFHR3 has been implicated in several diseases, including IgA nephropathy, atypical hemolytic-uremic syndrome, and biliary tract cancer." (PMID 40918463, 2025). "Polymorphism of the CFHR3 gene is associated with an increased risk of atypical hemolytic uremic syndrome." (PMID 35740418, 2022). "Complement factor H-related protein 3 (CFHR3), e.g., was one of several proteins that distinguished G4 and G5 from the other groups; it has been associated with the atypical hemolytic-uremic syndrome and defects in the complement alternative pathway." (PMID 35458690, 2022). "The combined deletion of CFHR3 and CFHR1 that is protective in AMD is associated with an increased risk for atypical hemolytic uremic syndrome." (PMID 21850184, 2011).
meningococcal disease (8 papers, 2013 to 2023). "Recently it has been shown that variants in CFH and CFHR3 are associated with susceptibility to meningococcal disease." (PMID 23613724, 2013). "Indeed, SNPs in both CFH and CFHR3 are associated with altered susceptibility for meningococcal disease." (PMID 27007437, 2016). "Studies of host susceptibility and bacterial genome-wide association studies (GWAS) highlight the importance of the interaction between fHbp and CFH and other complement factors, such as CFHR3, on the development of invasive meningococcal disease (IMD)." (PMID 36941192, 2023). "Of note, CFHR3 can be lost along with CFHR1, with this deletion being common in individuals from Northern Nigeria, where epidemics of meningococcal disease can start." (PMID 36941192, 2023).
IgA nephropathy (6 papers, 2017 to 2025). "A single deletion in both CFHR1 and CFHR3 confers a 30% reduction in the risk of IgA nephropathy, and a meta-analysis with risk-score model including Asian, European, and African population evaluated five susceptibility loci of three MHC, one CHF and one HORMAD2." (PMID 34354705, 2021). "Additionally, the genes CFHR1 and CFHR3, associated with the complement factor H family, have been identified as playing a role in inducing cellular senescence in the tubular cells of kidney allografts in patients with IgA nephropathy." (PMID 39602449, 2024). "A genome-wide association study of IgA nephropathy identified three independent loci in the major histocompatibility complex (MHC) and a common deletion in CFHR1 and CFHR3 that reached genome-wide significance, emphasizing the crucial role of complement activation in the disease." (PMID 28642464, 2017). "The deletion of the CFHR3 and CFHR1 genes is protective in IgA nephropathy presumably via the lack of FH competitors (FHR-1, FHR-3) on the surfaces, leading to more effective inhibition of complement activation by FH." (PMID 38410512, 2024).
hepatocellular carcinoma (5 papers, 2022 to 2024). A malignant tumor that arises from hepatocytes. "Overexpression of CFHR3 can affect the proliferation and apoptosis of hepatocellular carcinoma." (PMID 36860314, 2023). "However, the biological functions of CFHR3 in hepatocellular carcinoma (HCC) remain largely unclear." (PMID 35852862, 2022). "According to reports, CFHR3 may be a potential biomarker for the disease hepatocellular carcinoma (HCC); however, as the second highest type of cancer in the liver, the correlation between CFHR3 expression and its clinical significance of CCA remains unclear." (PMID 36213819, 2022).
systemic lupus erythematosus (4 papers, 2011 to 2021). An autoimmune multi-organ disease typically associated with vasculopathy and autoantibody production. "Moreover, CFHR3,1Δ has been associated with a lower risk for the development of AMD and IgAN, whereas it increases the risk for systemic lupus erythematosus (SLE) and aHUS (because of anti-Factor H autoantibodies)." (PMID 34682837, 2021). "The absence of an association of CFHR3-1Δ with renal disorder in lupus suggests that CFHR3 and CFHR1 play a different role from CFH in the pathogenesis of lupus, although further studies are required to validate the lack of association between the CFHR3-1Δ deletion and renal disorder in SLE." (PMID 21637784, 2011).
C3 glomerulopathy (2 papers, 2021 to 2024). "Complement dysregulation involving the CFHR3 gene mutation responsible for aHUS traditionally encompasses the histopathological picture of thrombotic microangiopathy and C3 glomerulopathy, and usually presents with rapidly progressive renal failure." (PMID 39184759, 2024).
lupus nephritis (2 papers, 2021 to 2022). Glomerulonephritis in the context of systemic lupus erythematosus. "In line with previous studies showing that a higher CFHR3 level in lupus nephritis was positively correlated with SLEDAI values, our results indicated that the CFHR3 level was higher in the non-CAKUT group." (PMID 35740418, 2022). "The levels of CFHR3 and CFHR5 found in plasma were higher in patients with lupus nephritis than in healthy individuals, and patients with both high CFHR3 and high CFHR5 exhibited the shortest progression-free survival." (PMID 35095896, 2021).
macular degeneration (2 papers, 2023 to 2024). Loss of vision in the central portion of the retina (macula), secondary to retinal degeneration. "In addition, we observed CFHR3 to be associated with macular degeneration, and OMG and ITIH1 to be associated with height." (PMID 38540773, 2024).
retinal degeneration (2 papers, 2018 to 2021). Degeneration of the retina. "FHR-3 is also produced in the retina, and its contribution to retinal degeneration by inhibiting FH binding to C3b and modified surfaces has been suggested; nonetheless, the relevance of the CFHR3*A and CFHR3*B variants in AMD has not been addressed." (PMID 30050540, 2018).
atherosclerosis (1 paper, 2022). A disease characterized by the build-up of fatty material and calcium deposition in the arterial wall resulting in partial or complete occlusion of the arterial lumen. "The most important modulators of CFH binding to MDA-epitopes – the CFH variant Tyr402His and the deletion of CFHR3&CFHR1 genes – are frequent in the population and affect the development of the two most common diseases, atherosclerosis and AMD." (PMID 36248824, 2022). "Deletion of CFHR3&CFHR1 genes offers protection in both of them, while Tyr402His is deleterious in AMD and possibly atherosclerosis, highlighting CFH’s importance in homeostatic responses." (PMID 36248824, 2022).
C3 glomerulonephritis (1 paper, 2023). Glomerulonephritis characterized by C3 accumulation with little or absent deposition of immunoglobulin, in the absence of ultrastructural electron-dense transformation seen in dense deposit disease. "The rare variant of CFHR3 has been reported in C3 glomerulonephritis." (PMID 37845399, 2023).
cholangiocarcinoma (1 paper, 2022). A carcinoma that arises from the intrahepatic biliary tree (intrahepatic cholangiocarcinoma) or from the junction, or adjacent to the junction, of the right and left hepatic ducts (hilar cholangiocarcinoma). "First, we found that decreased CFHR3 expression was associated with a poor prognosis in cholangiocarcinoma patients, including overall survival and recurrence-free survival." (PMID 36213819, 2022). "A higher expression of CFHR3 in normal tissues and a lower expression in cholangiocarcinoma tissues was observed in TCGA datasets." (PMID 36213819, 2022). "As the curves shown, cholangiocarcinoma patients with lower CFHR3 expression showed a lower OS (log-rank p = 0.0036) and a poorer DFS (log-rank p = 0.038)." (PMID 36213819, 2022). "In immune regulation analysis, we identified that the expression level of CFHR3 had a positive correlation with infiltrating levels of B cells, neutrophils, and macrophages, but correlated negatively with cholangiocarcinoma cells, CD8+ T cells, and monocytes." (PMID 36213819, 2022). "TCGA datasets and GEO datasets revealed an elevated expression level of CFHR3 in normal tissues as well as a lower expression level in cholangiocarcinoma tissues in the present research." (PMID 36213819, 2022). "The coexpression method was used to predict the correlations among DElncRNAs, DEmiRNAs, and DEmRNAs with CFHR3 expression in patients with cholangiocarcinoma." (PMID 36213819, 2022). "Here, we identified CFHR3 as a key gene and hypothesized that CFHR3 has a correlation with prognosis and immune regulation of cholangiocarcinoma." (PMID 36213819, 2022). "Therefore, CFHR3 could be a biomarker for prognosis in cholangiocarcinoma." (PMID 36213819, 2022).
chronic kidney disease (1 paper, 2024). Impairment of the renal function secondary to chronic kidney damage persisting for three or more months. "The effect of CFHR3 gene mutation on renal interstitial compartment presenting as chronic interstitial compartment should be considered in cases of young-onset chronic kidney disease with a strong family history of ESRD and low C3 levels." (PMID 39184759, 2024).
complement deficiencies (1 paper, 2025). "Next-generation sequencing, covering approximately 5,000 genes, including those associated with familial HLH, and wide range of IEI and complement deficiencies (such as C3, CFB, CFH, CFHR1, CFHR3, CFHR5, CFI) and MLPA analysis for CFHR1/CFHR3 deletions, was performed." (PMID 40995360, 2025).
Fanconi anemia (1 paper, 2022). Fanconi anemia (FA) is a hereditary DNA repair disorder characterized by progressive pancytopenia with bone marrow failure, variable congenital malformations and predisposition to develop hematological or solid tumors. "We found that the lower mRNA expressions of C1R, C6, C7, CFP, and CFHR3 were correlated with pathways like Fanconi anemia pathway, cell cycle, MicroRNAs in cancers, and so on." (PMID 34813686, 2022).
gallbladder carcinoma (1 paper, 2022). "Elevated expression of CFHR3 has been observed in gallbladder carcinomas compared with that in adjacent tissues." (PMID 35549979, 2022).
glioma (1 paper, 2022). A benign or malignant brain and spinal cord tumor that arises from glial cells (astrocytes, oligodendrocytes, ependymal cells). "Loss of CFHR3 function in gliomas induces cisplatin resistance." (PMID 35549979, 2022).
HIV-1 infection (1 paper, 2005). The type species of lentivirus and the etiologic agent of acquired immunodeficiency syndrome (AIDS). "Several genes have been established as important for HIV-1 infection and replication, including Pou2AF1 (OBF-1), complement factor H related 3, CD4 receptor, ICAM-1, NA, and cyclin A1." (PMID 15780141, 2005). "As observed in both tables and the initial screening of genes displaying at least two present calls, several genes have been established as important for HIV-1 infection and replication, including OBF-1, complement factor H related 3, CD4 receptor, ICAM-1, NA, and cyclin A1." (PMID 15780141, 2005).
meningococcal meningitis (1 paper, 2020). "For meningococcal meningitis, loci within the complement factor H (CFH) gene and CFH-related protein 3 (CFHR3) in the host were associated with susceptibility to disease." (PMID 33262994, 2020).
neuroblastoma (1 paper, 2015). Neuroblastoma (NB) is the most common solid, extracranial childhood tumor. "Kaplan-Meier plots showed a significant association between increased expression of CFHR3, MDFIC, CSMD3, FOXP2, or RALYL (genes with gains in coding regions) and poor OS in patients with neuroblastoma." (PMID 26159519, 2015).
Obesity (1 paper, 2020). Accumulation of substantial excess body fat. "They complement regulation associated with lipoproteins and lipid metabolism and adipogenesis, encompassing CFHR1, CFHR3, and BMPR2 protein–protein interactions, given marked obesity is a common finding in PWS." (PMID 32384786, 2020).
rheumatic diseases (1 paper, 2012). "Since in aHUS an association was reported between the presence of FH-autoantibodies and homozygous deletions of the gene encoding CFHR1 and CFHR3, we now also analyzed whether there is such an association in rheumatic diseases." (PMID 22894814, 2012).
rheumatoid arthritis (1 paper, 2022). A chronic, systemic autoimmune disorder characterized by inflammation in the synovial membranes and articular surfaces. "Although the relation between OSE-binding and FHR-3 has not been investigated in diseases associated with a high level of oxidative stress, in many of them, e.g., rheumatoid arthritis and SLE, FHR-3 serum levels are increased, and the lack of CFHR3 gene is protective." (PMID 36248824, 2022).
Sepsis (1 paper, 2016). Sepsis is defined as life-threatening organ dysfunction caused by a dysregulated host response to infection. "We cannot formally exclude an acute phase protein response in some of the sepsis patients that we tested as we were not able to measure FHR-3 under healthy conditions in these patients and we had no DNA to verify the CFHR3 CNV status in these individuals." (PMID 27007437, 2016).